IL1B (interleukin 1 beta)
Diseases named in the same sentence as IL1B in open-access papers (continued):
Sharing a sentence is not in itself a finding about the gene and the disease.
infection (continued). "We also measured the levels of pro-inflammatory cytokines IFNγ, TNFα, IL-12, and IL-1β in cultured supernatant collected after 24, 48, and 72 h post infection to verify if the levels of these cytokines have any correlation with CD200 expression in parasite-infected DCs." (PMID 29915577, 2018). "A major disadvantage of these approaches might be the general inhibition of IL-1β that should result in an impaired host defense against infections." (PMID 30105015, 2018). "However, the infection by H. pylori is more likely among patients with IL-1β-31 CT and TT genotypes in regions of Asia and Latin America than in those with IL-1β-31 CC." (PMID 30123433, 2018). "In addition, several researchers have reported the important role of inflammasome activation and of the generation of an IL-1β inflammatory response during infection with P. brasiliensis." (PMID 29780375, 2018). "Similarly, exogenous treatment of keratinocytes with recombinant IL-1β during wild-type GAS infection resulted in a 5–10% increase in cytotoxicity compared to wild-type infection alone at 6 h post-infection." (PMID 30018884, 2018). "However, a higher level of interleukin-1β (il-1β) expression was detected in BL23 group than in the control group at 8 h post-infection (P < 0.05)." (PMID 30233415, 2018). "IL-1β is crucial in host-defenses towards infection and injury." (PMID 30089163, 2018). "Treatment with the caspase-1 inhibitor YVAD-CHO in combination with PGE2 abolished release of IL-1β upon infection with both Y. enterocolitica and S. Typhimurium, supporting the fact that caspase-1 is responsible for the PGE2-triggered stimulation of inflammasome." (PMID 30429830, 2018). "In addition, NLRP1 silencing in human monocytes led to reduced production of IL-1β and greater rates of cellular infection." (PMID 30619358, 2018). "Upon infection, TLRs recognized pathogens and resulted in the phosphorylation and degradation of IκB; then NF-κB is free to translocate into the nucleus and promote the expression of many inflammatory mediators, such as IL-1β and IL-6." (PMID 29681986, 2018). "Moreover, significantly more IL-1β protein was released in response to AF2122 infection than G18 infection from 24 hpi onwards (P < 0.001)." (PMID 29263113, 2018). "Infection in keratinocytes with 16QsV up to 4h led to an increase of IL-1β transcripts." (PMID 30089163, 2018). "After 17 hours of infection, secretion of IL-1β into the supernatant was evaluated." (PMID 30589883, 2018). "Taken together, oral administration of B.s-Dia could improve host defense against infections, at least in part through the positive regulation of IL-1β and the negative regulation of TGFβ–IELs axis." (PMID 28491061, 2017). "Of notice, prolonged infection with WT P. aeruginosa (6 or 8 h), but not with ΔlasR/rhlR, caused a manifest degradation of caspase-1 and IL-1β in the culture supernatants." (PMID 28396663, 2017). "The streptococcal cysteine protease SpeB has previously been shown to directly cleave pro-IL-1β into its mature form, and a recent study implicates this virulence factor in inflammasome-independent IL-1β maturation in a murine model of GAS infection as well as in infection of murine BMDMs in vitro." (PMID 28720729, 2017). "The down modulation of IL-1β is a further evidence of mDC dysfunction during the infection." (PMID 28747721, 2017). "First, p62 and many other chaperones are stress-responsive, possibly to ensure different substrates are properly degraded under certain conditions; similarly, ANGPTL8 is a stress-responsive molecule with enhanced expression under TNFα, IL-1β, LPS, or infection." (PMID 29255244, 2017). "It is conceivable that in immunocompetent individuals, the low level of IL-1β does not cause any problems as other effector mechanisms can keep the infection under control." (PMID 28225025, 2017).
infection (continued). "Infection of chicken kidney cells (CKCs) with Escherichia coli caused a reduction of IL-1β compared to non-infected control, but infection with S. typhimurium or S. dublin led to significantly increased IL-1β transcripts." (PMID 28854912, 2017). "However, expression of the active form of IL-1β was evident with a 2.00-fold increase at 20 wpi only in mice with a medium-dose infection." (PMID 29273062, 2017). "HCMV also partially blocks TNF-α signaling through downregulation of TNFR1 surface expression during lytic infection, while IL-1β- and TNF-α-induced expression of the chemokine monocyte chemoattractant protein 1 (MCP-1) is blocked at the level of transcription." (PMID 28270578, 2017). "As infection progressed, we detected a robust upregulation of genes encoding cytokines and chemokines (CCL2, CCL3, IL1B, CXCR1, IL1RN) as well as granulocyte associated transcripts (TLRs 1-4, SPI1, S100A8, S100A9, CD177), which correlated with the higher numbers of granulocytes 5 DPI." (PMID 28852031, 2017). "The genes with strongest induction included chemokines (e.g. CXCL11, 84-fold; CXCL10, 18-fold; CXCL9, 9-fold; CCL2, 9-fold) and cytokines (e.g. IL6, 54-fold; IL12B, 10-fold; IL1B, 9-fold;) etc. consistent with the infection of host phagocytes with Mtb reported earlier by us." (PMID 28880895, 2017). "Further enhancement of neutrophil accumulation could be mediated by chemotactic factors stimulated by inflammatory cytokines IL-1β and TNFα, which we found increased with infection." (PMID 28591228, 2017). "We therefore investigated whether Syk signaling was required for NLRP3 inflammasome-dependent caspase-1 activation and IL-1β production following SEA infection." (PMID 28808303, 2017). ", and both also had the greatest decrease between explantation and reimplantation demonstrating infection resolution (12.4-fold decrease for IL-1β; 11.2-fold decrease for IL-6), implicating IL-1β and IL-6 as potentially the most applicable for usage in diagnosis/prognosis of PJI." (PMID 28487810, 2017). "A further increase in the abundance of SAA1 in the amnion is expected in the presence of infection for the reason that the proinflammatory cytokines such as IL-1β could stimulate SAA1 production in cultured amnion fibroblasts." (PMID 28386088, 2017). "Only gut epithelial cells specifically reacted to NMI infection with a significant upregulation of IL-1β, lung epithelial cells with a specific downregulation of IL-6 whereas infection with NMII resulted in a distinct up-regulation of TNF-α in lung epithelial cells." (PMID 28403908, 2017). "IOE infection of TLR7-/- BMM elicited IL-1β at slightly lower levels when compared to WT-BMM." (PMID 29049365, 2017). "Because the AIM2 inflammasome plays an important role in the host defense against infection, we investigated whether the association between pUL83 and AIM2 affects the subsequent assembly of the inflammasome and IL-1β activation." (PMID 28219398, 2017). "Taken together, these studies suggest that TLR- and inflammasome-dependent IL-1β production is required for host defense to bacterial infection, but may become detrimental in the case of overwhelming infections." (PMID 28704551, 2017). "Microglial cells could be rapidly activated in response to infection, inflammation, or brain injury, and thus lead to the releases of various inflammatory mediators, including IL-1β, IL-6, TNF-α, nitric oxide, reactive oxygen species, and prostaglandin E2." (PMID 28804270, 2017). "To determine whether PFOS promoted the function of ILC3s and Th17 cells by inducing IL-1β or IL-23, we isolated LPL from C. rodentium infected mice on day 5 post infection and analyzed the mRNA expression of IL-1β and IL-23 by real-time RT-PCR." (PMID 28701769, 2017). "In macrophages derived from peripheral blood of healthy donors (MDMs), we could confirm infection specific alterations in the expression of IL1B, ACSL1, ATG13 and RAB8B isoforms as noted in THP-1 macrophages." (PMID 28257432, 2017).
infection (continued). "We found that whereas C57BL/6 macrophages readily triggered the production of IL-1β after 24 hours of infection with flagellated bacteria, the Casp1/11-/- or Asc/Casp1/11-/—deficient cells do not trigger a IL-1β production." (PMID 28771586, 2017). "Inflammatory processes comprise a critical response to pathogenic infection; however, the excessive production of inflammatory cytokines, such as TNF-α and IL-1β, may induce cell injury." (PMID 28821873, 2017). "Taken together, these studies suggest that dysregulated IL-1β responses are detrimental to infection control, including both overly vigorous and restrictive responses, and that appropriate levels induced during infection are crucial for the survival of an infected host." (PMID 28720729, 2017). "Given that alterations in placental HSD11B2 expression are seen in pregnancies complicated with stress or infection, we next sought to determine if the biological mediators of stress (Cort) and infection (IL-1β) altered 11β-HSD2 protein expression at the cellular level." (PMID 28321257, 2017). "IL-1β mediates the expression of a vast array of genes involved in secondary inflammation, which coordinate all aspects of local inflammation and also attract and activate the cells of the adaptive immune system at the infection sites." (PMID 28914761, 2017). "Importantly, the wt and nga(G330D) strains induced comparable levels of IL-1α upon infection of macrophages, suggesting that increased IL-1β levels induced by the nga(G330D) strain is governed by a specific, likely posttranslational, mechanism." (PMID 28720729, 2017). "Indeed, increased leukocyte recruitment to the brain of IFN-α/βR −/− mice was detected after 6 days of infection and was associated with elevated levels of inflammatory mediators, such as the chemokines CCL5 and CXCL1 and the cytokines IL-1β and TNF-α." (PMID 28442607, 2017). "We suggest that IL-1β and IL-12 can limit the infection, preventing further progression of IE." (PMID 28659664, 2017). "Thus, caspase-6 seems to affect the expression of IL-10 and IL-1β in a very early stage after infection." (PMID 28686630, 2017). "However, we detected lower concentrations of IL-17 upon infection with the yeast-locked mutant, reflecting potential differences between innate lymphoid cell and γδ-T cell responses that depend on IL-1β and adaptive Th17 cell polarization." (PMID 28314592, 2017). "Infection induces upregulation of pro-IL-1β in CD103+ and CD11b+ DCs as well as in neutrophils." (PMID 28671985, 2017). "However, the och1Δ/Δ strain induced significantly less IL-1β in the liver at day 7 post-infection compared to WT CLIB." (PMID 28713338, 2017). "Neutrophils primarily eliminate pathogens in two ways: (i) secretion of cytokines and chemokines, such as interleukin (IL)-1b, IL-18 and IL-37, to recruit and activate additional phagocytes to the infection site; and (ii) phagocytosing microbes, primarily dependent on their granules." (PMID 28835569, 2017). "We also measured cytokine production after C. albicans restimulation of splenocytes obtained from 2-DG or BPTES-treated mice after the infection, finding a significant reduction in the production capacity of IL-1β, IL-6, IL-10, TNFα and IFNγ in mice treated with 2-DG." (PMID 28922415, 2017). "To determine the involvement of the upstream and the downstream signals of IL-1β, we assessed the expression levels of the upstream NLRP3 inflammasome in dendritic cells and different glial cells from resistant B6 and susceptible SJL mice after TMEV infection." (PMID 28445497, 2017). "We show that neutrophils serve as an early source of il1β that may contribute to the containment of the disease by recruiting macrophages to sites of infection and hence enabling granuloma formation." (PMID 28747644, 2017). "During local infections, this type I IFN can impair host defense, whereas in severe infections, this type I IFN can diminish systemic inflammation caused by overproduction of IL-1β." (PMID 28704551, 2017).
infection (continued). "Similar to the observations in the β2M-deficient mice, we found that IL-1β levels were not reduced in the spleen of Perforin-deficient mice compared to wild-type mice in the infection models." (PMID 28537251, 2017). "To define the inflammasome complexes that contribute to IL-1β secretion following infection with virulent IOE and regulated by MyD88, we further analyzed mRNA expression of several inflammasome complexes (NLRP3, NLRC4, AIM2) in the liver tissues of WT and MyD88-/- mice on day 7 p.i with IOE." (PMID 29049365, 2017). "Infection of macrophages from STING deficient mice with C. trachomatis failed to induce interferon-β expression and exhibited reduced IL-1β secretion, cell death and reduced IL-1β processing and caspase-11 expression but had equivalent responses to LPS/ATP stimulation." (PMID 28570638, 2017). "Thus, IL-1β is an important mediator in infection that stimulates intrinsic, innate and adaptive immune pathways as well as IL-6, which contributes to host defense through the stimulation of acute phase responses, hematopoiesis and immune reactions." (PMID 28737707, 2017). "Infection with α-glucan-deficient chemotype I H. capsulatum was associated with greater pulmonary levels of IFN-γ, IL-1β, IL-12, and TNFα, in association with increased weight loss, more severe pathology in lung histology, and higher pulmonary fungal burden later in the infection." (PMID 29371564, 2017). "Thus, among the cell populations evaluated, it was discovered that DCs (right) are the major cell producing IL-1β in the TG during infection." (PMID 28222752, 2017). "We document a sharp increase in the inflammatory response in terms of Ifng, Tnfa, Il6, Il1b, Il1r1, Cxcl9 and Cxcl10 expression already on day 6 post-infection in WT mice, and of Cd8a on day 7, which were essentially absent in ST2-/- mice on day 5 to 7 after PbA-infection." (PMID 28448579, 2017). "We conclude that P2X7 receptor activation inhibits T. gondii growth via ROS generated, most likely, from NADPH oxidase (rather than mitochondrial ROS), while also activating the canonical NLRP3 inflammasome, which leads to IL-1β secretion and infection control via mitochondrial ROS production." (PMID 29075257, 2017). "Notably, infection with X4550(pYA3334-SspH2-EscI) induced significantly more IL-1β and IL-18 secretion from peritoneal macrophages than that induced by X4550(pYA3334-SspH2) or X4550(pYA3334) (P < 0.05)." (PMID 28468643, 2017). "The amount of particles/mL in this so called 100 k pellet increased with multiplicity of infection, which could also be observed upon administration of the sterile stimulant IL-1β." (PMID 28740179, 2017). "Prominent among inflammatory pathways in monocytes/macrophages are caspase-1-activating platforms called “inflammasomes” that control maturation and secretion of interleukins such as IL-1β and IL-18, whose potent pro-inflammatory activities direct host response to infection and injury." (PMID 28489580, 2017). "To test whether this finding extends to tissue resident DCs, we monitored secretion of IL-1β and of IL-18 (which is undetectable in BMDCs) by splenic DCs after infection with flagellin-expressing STm." (PMID 29253868, 2017). "IL-1β, IL-10, KC, and G-CSF levels were all induced by infection." (PMID 28672877, 2017). "In late infections reduction in IL-1β might have reduced Caspase 1 expression as there are reports that IL-1β secretion and reactive oxygen species (ROS) down-modulate IL-1β rather than activating it in phagocytes." (PMID 27932936, 2016). "This could be because infection by H. pylori may directly induce an inflammatory response in which IL-1β is present, thus already saturating the need for IL-1β activity." (PMID 27525003, 2016). "In addition, infection with ST had negligible effects in the mRNA levels of Gbp4 in both neutrophils and macrophages, while both cells showed increased mRNA levels of il1b on infection." (PMID 27363812, 2016).
infection (continued). "Consistent with such a role, Il1b-/- mice were protected from infection and pathology." (PMID 27732661, 2016). "In contrast, M28 GAS elicited significant cytokine increases in TNF-α, IL-17A, IL-6, IL-1β, and IL-22, as early as 3 to 7 days post-infection in the estradiol pulse model, and a significant cellular infiltrate in the lumen was observed in colonized WT mice compared to non-infected or IL-17A−/− mice." (PMID 27241677, 2016). "Furthermore, enhanced antifungal activity of human neutrophils prior to activation with IFN-γ, GM-CSF, and/or IL-1β has been described, suggesting an important role of these phagocytic cells in host resistance during early infection with P. brasiliensis." (PMID 27642235, 2016). "IL-1β and IL-10 were also upregulated in goldfish (Carassius auratus) kidney-derived monocyte/macrophage cultures in vitro and goldfish kidney tissue in vivo following infection with M. marinum." (PMID 27415626, 2016). "Moreover, increased IL-1β expression was observed in both local and systemic infections in other tissues, such as the gills and the tail fin." (PMID 27540375, 2016). "However, bladder macrophages exhibited increased expression of pro‐inflammatory cytokines that can promote iron retention, as evidenced by increased expression of IL‐6 and IL‐1β upon infection." (PMID 27980776, 2016). "As, ROS upregulate Caspase 1 as well as IL-1β, So increase in ROS production on Riboflavin treatment might have upregulated Caspase 1 as well as IL-1β in early infections." (PMID 27932936, 2016). "However, there were marked increases in the expression of IL-1β and IL-6 post-infection with CK/SD/w3 at 12 hpi (P > 0.05) and 18 hpi (P < 0.05), respectively, reaching the highest expression at 24 hpi (IL-1β at 19-fold and IL-6 at 21-fold, P < 0.01)." (PMID 27446066, 2016). "Even though infecting mice with 107 CFU of KN99α caused the stimulation of both IL-1α and IL-1β, the levels were only comparable to those induced by infection with 106 CFU of the cda1Δ2Δ3Δ mutant, which was nonprotective." (PMID 27165801, 2016). "Furthermore, cytokine levels from vaginal washes of M28 GAS infected Rag1−/− and WT mice demonstrated that the Rag1−/− mice produced greater quantities of IL-1β, IL-6, and TNFα at 14, 21, and 28 days post-infection compared to WT mice." (PMID 27241677, 2016). "In mice consuming the WB-enriched diet, the expression of the Th17 cytokine, Il-17A was lower than mice consuming the RS-enriched and CN diets during peak infection, and by late infection, these mice exhibited the lowest expression of Th1 (Il-1β, Ifnγ, Tnfα) cytokines." (PMID 28031748, 2016). "IL-1β is a vital proinflammatory cytokine that mediates immune functions and participates in the resistance to mycobacterial infections during the early stages of infection." (PMID 26881918, 2016). "Interestingly, IL-1β production was significantly reduced following Ft LVS or SchuS4 infection of cells from Nlrp3-/- mice." (PMID 27926940, 2016). "We examined here the cell types and mechanisms involved in IL-1β production during infection." (PMID 27509078, 2016). "In the present study, after finding that neutrophils make a significant contribution to IL-1β production during infection, we observed that live GBS induce in these cells activation of endosomal TLRs and of the caspase-1 inflammasome, leading to the release of mature IL-1β." (PMID 27509078, 2016). "Furthermore, IL-1β remained elevated at 48 hours post infection in mice receiving 109 CFUs (100.3 ± 13.02 pg/ml) while they became undetectable in mice receiving 108 CFUs." (PMID 27303806, 2016). "Furthermore, it has been shown that binding of vitamin D induces IL-1β secretion and prevent infection." (PMID 27014247, 2016). "Indeed, the increased production of type I IFNs in response to infection in Axl-/- cells limited the production of IL-1β, a cytokine required for the effective priming of antiviral T cells." (PMID 27350258, 2016).